COL1A1 (collagen type I alpha 1 chain)
Diseases named in the same sentence as COL1A1 in open-access papers (continued):
Sharing a sentence is not in itself a finding about the gene and the disease.
liver fibrosis (continued). "Western blot analysis supported these findings, demonstrating that LTH-sEVshCtr further enhanced the expression of liver fibrosis markers COL1A1, COL3A1, and α-SMA protein in the liver tissue of HFD mice." (PMID 38822260, 2024). "Knockdown of NEAT1 in primary HSCs inhibited cell proliferation by 54% and suppressed expression of fibrogenic molecules, αSMA and COL1A1, resulting in improvement of liver fibrosis." (PMID 39872125, 2024). "The mRNA and protein levels of liver fibrosis markers αSMA and Col1a1 were investigated in excised liver tissues." (PMID 39264964, 2024). "Female Gpr183–/– mice showed a trend of overall lower levels with significantly lower levels of liver fibrosis markers Col1a1 and Mcp1 compared to WT females, a pattern opposite of that observed in VAT macrophage infiltration." (PMID 39545055, 2024). "INT-787 treatment induced significant dose-dependent reductions of liver Col1a1, a major contributor to hepatic fibrosis." (PMID 38662778, 2024). "The Col1a1 isoform is a key fibrillar collagen involved in liver fibrosis and both Col1a1 mRNA and protein were reduced by INT-787 treatment." (PMID 38662778, 2024). "Subsequently, we successfully induced the LX2 cell model of liver fibrosis, as evidenced by a significant increase in the expression of the liver fibrosis marker gene COL1A1." (PMID 38429802, 2024). "The transcriptional level of Col1a1 (marker of hepatic fibrosis) was significantly higher in the L-arabinose-treated group." (PMID 38980058, 2024). "In fact, one of the most significantly upregulated genes in Adn-Lpin1–/– livers is Col1a1, which clusters to the turquoise model and is a marker of activated stellate cells, the primary mediators of hepatic fibrosis." (PMID 39405118, 2024). "Increased SNHG5 and collagen type I alpha 1 chain (Col1A1) (liver fibrosis-related marker) were found in aHSCs compared with qHSCs." (PMID 38438584, 2024). "In mice, the inhibition of IL-17A showed reduced mRNA levels of profibrogenic genes, such as COL1A1, and a reduced degree of liver fibrosis." (PMID 36625344, 2023). "These NASH liver organoids showed the appearance of cells with dendritic-like morphology and the increased expression of liver fibrosis-related genes such as Collagen type I alpha 1 (Col1a1), Actin alpha 2 (Acta2), and others." (PMID 37900170, 2023). "The qRT-PCR assays showed that Dbn1, Col1a1, and Col3a1 expression levels increased during CCl4-induced hepatic fibrosis." (PMID 36690273, 2023). "The Bacteroides treatment improved the liver/body weight ratio and normalized hepatic fibrosis biomarkers, including COL1A1." (PMID 37819146, 2023). "Deoxyelephantopin decreased the expression of a-SMA and α1(I) procollagen II (pro-COL1A1) and inhibited liver fibrosis." (PMID 37663261, 2023). "α-SMA (alpha-smooth muscle actin) and Col1a1 (type I collagen alpha 1 chain) are common indicators for assessing the degree and progression of liver fibrosis in NASH." (PMID 37081966, 2023). "This was further confirmed by augmented expression of collagen type I alpha 1 (COL1A1) mRNA, which is consistent with the characterization of liver fibrosis in transgenic mice." (PMID 38132319, 2023). "MitoQ administration reduces the expression of liver fibrosis proteins such as Col1A1 and the active form of caspase 3, which represents the executive apoptosis protease." (PMID 37834219, 2023). "These mice showed higher HBV RNA, DNA, HBV core antigen (HBcAg), and HBV surface antigen (HBsAg) levels after liver fibrosis induction as judged by a rise in Col1a1, SMA, MMPs, and TIMPs mRNAs and by increased liver stiffness." (PMID 37600826, 2023). "We have previously demonstrated that in cirrhotic rats MitoQ decreases the expression of Col1A1 and TGFβ-1 and improves liver fibrosis." (PMID 37107346, 2023). "Liver fibrosis occurs when HSCs, which normally store vitamin A, differentiate into myofibroblasts and secrete collagens, including Col1a1, abnormally upon various stimuli." (PMID 37509702, 2023).
liver fibrosis (continued). "Liver fibrosis in NAFLD is caused by liver inflammation, and major markers of fibrosis are Col1a1, Col3a1, and Tgfβ1." (PMID 37894124, 2023). "We saw an approximately onefold increase in total liver bile acid levels and more than a onefold increase in liver fibrosis levels, gauged by Col1a1 expression and total liver collagen levels." (PMID 37626991, 2023). "The abnormal synthesis of α-SMA and COL1A1 was found in the model group after liver damage compared with the sham group, and both are considered important molecular markers of liver fibrosis." (PMID 37513376, 2023). "Along these lines, miR-23a and miR-28a were found to decrease COLα1 (I) protein levels in a CCl4 induced mouse model of liver fibrosis, and miR-1954 to reduce Col1a1 mRNA levels in an angiotensin II-induced mouse model of cardiac fibrosis." (PMID 37373151, 2023). "Gene expression of Col1a1, TGFβ-1, TIMP-1, MMP-2, and MMP-9, which are associated with liver fibrosis, was significantly higher in MCDHFD mice than in control animals." (PMID 37107346, 2023). "The temporal CDAHFD-feeding experiment revealed that Dbn1 expression was induced as the hepatic fibrosis progressed, along with increase in Col1a1 and Col3a1 expression." (PMID 36690273, 2023). "In conclusion, the COLEC10 overexpression in vivo promoted the mRNA expression of Col1a1 and Vegfa, which suggested that the COLEC10 is associated with the ECM alteration and angiogenesis in the pathogenesis of liver fibrosis." (PMID 38036508, 2023). "CTGF silencing in liver fibrosis rodent models has shown to cause a decrease in the transcription of TGFB1, ACTA2 and COL1A1." (PMID 36672237, 2023). "The significant enrichment of hepatic fibrosis/hepatic stellate cell activation (z = 0, p < 1e-5) largely due to the downregulation of several collagens (COL1A1, COL4A1, and COL4A2) was present in cluster 4 that contained nearly all control iAstros." (PMID 36590162, 2023). "Silencing Fstl1 using shRNA can reduce Col1a1 mRNA expression and macrophage accumulation in carbon tetrachloride injury-mediated liver fibrosis in mice." (PMID 37770480, 2023). "The results demonstrate the COLEC10 promoted the expression of Col1a1 and Vegfa, which indicates the function of COLEC10 is associated with the ECM alteration and angiogenesis during the liver fibrosis." (PMID 38036508, 2023). "Along these lines, an increase in Col1a1 mRNA expression was also observed in a rat model of liver fibrosis established by administering CCl4 in comparison to healthy controls." (PMID 37373151, 2023). "Altogether, losartan treatment reduced liver fibrosis, inhibited Col1a1 deposition, and blunted the generation of immunosuppressive CAF." (PMID 37126700, 2023). "Then, the effect of PC on liver fibrosis was further examined by identifying the characteristic indicators of liver fibrosis, including COL1A1, Lama1, and Timp1." (PMID 35721129, 2022). "HE staining, Masson staining, and the IHC staining showed an increase in COL1A1 and vWF protein expression in the first stage of CCl4-induced liver fibrosis." (PMID 36497176, 2022). "CHCHD2 knockout greatly suppressed TAA-induced liver fibrosis, as evidenced by Sirius red staining and reduced expression levels of Des, Timp1, transforming growth factor-β (Tgfb), Col1a1 (P = 0.055), and Col3a1 (P = 0.054)." (PMID 36477358, 2022). "We demonstrate that the administration of RSV effectively improves liver function and ameliorates liver fibrosis by reducing collagen deposition and reversing the expression of COL1A1 and PPAR-γ." (PMID 35080697, 2022). "qPCR analysis showed that the expression of Tgf-β1, which promotes liver fibrosis, was lower in p62-mRes mice, but the expression of other markers of inflammation (Tnfa and Il-1β) and fibrosis (Col1a1) were unaffected." (PMID 36439272, 2022). "To further study role of RSV on liver fibrosis, we then evaluated the levels of COL1A1 and PPAR-γ in livers." (PMID 35080697, 2022).
liver fibrosis (continued). "Col1a1 is a valid target for the treatment of liver fibrosis by inhibiting the synthesis of type I collagen, which has been proven in many studies." (PMID 36313326, 2022). "Along with this, the mRNA levels of several liver fibrosis-related genes (Col1a1, Mmp9, Timp1) were also increased in livers from Gm4951−/− mice." (PMID 35842425, 2022). "We also measured hepatic expression of genes involved in detoxification/drug metabolism (Cyp1a1, Cyp1b1), inflammation (Il1b) and hepatic fibrosis (Col1a1)." (PMID 35788891, 2022). "Detection of the mRNA levels of a series of liver fibrosis-related molecules: Acta2, Col1a1, Tgfb1, and Timp1 in livers from IL-21−/−p40−/−IL-2Ra−/− mice and controls suggested no significant change of liver fibrosis." (PMID 35300072, 2022). "In this study, our steatohepatitis model demonstrated a rapid progression of hepatic fibrosis, even at 8 weeks, and pemafibrate completely suppressed Col1a1, Col1a2, and Ccl5 mRNA, which are involved in fibrosis." (PMID 35194060, 2022). "The level of fibrosis‐related genes (Acta2, Col1a1 and Timp1) was increased in liver injury groups for 10 weeks compared to 4 and 6 weeks, which confirmed the extent of liver fibrosis evaluated by fibrosis score." (PMID 33410581, 2021). "On the other hand, it was also reported that Nrf2 activation inhibited the early stage of hepatic fibrosis, reducing Col1a1 and α-SMA levels." (PMID 33499218, 2021). "Intravenous administration of miR‐29a has been reported to improve liver fibrosis in mouse models via the downregulation of Col1a1 expression." (PMID 33529442, 2021). "The authors found that hepatic expression of Col1a1 was elevated in ASH patients and correlated with hepatic LCN2 expression, and Lcn2-deficient mice were protected from liver fibrosis caused by either ethanol or CCl4 exposure." (PMID 34675931, 2021). "In vitro, RNF2 activates the expression of Col1A1 and αSMA in LX-2 cells through the Erk/p38 pathway, which is considered to be a potential target for regulating liver fibrosis." (PMID 34853322, 2021). "In line with decreased liver fibrosis and injury in Oxy210‐fed mice, hepatic expression of collagen (Col1a1) and α‐smooth muscle actin (Acta2) were substantially reduced." (PMID 34505423, 2021). "The upregulation of COL1A1 induced by dietary challenge suggests its potential involvement in liver fibrosis." (PMID 33777102, 2021). "Our results indicate that rSjP40 can inhibit the expression of COL1A1 in LX-2 cells, which is consistent with our previous results, demonstrating that rSjP40 can inhibit liver fibrosis by inhibiting the synthesis of COL1A1 in HSCs." (PMID 34820381, 2021). "Next, we measured the mRNA expression of genes involved in ECM accumulation and liver fibrosis like Fn1 and collagen type I (COL1A1, Col1a1)." (PMID 35087411, 2021). "Similar to the CCl4 model, Treg cells significantly were increased in the liver by feeding the diet and Treg depletion aggravated liver fibrosis assessed by liver fibrotic regions and expression levels of Col1a1 and Acta2 (α-SMA)." (PMID 33178216, 2020). "The observed sevelamer-mediated attenuation of hepatic fibrosis coincided with a decline in the hepatic expression levels of profibrotic genes including Col1a1, Acta2, and Tgfb1." (PMID 32575352, 2020). "Suppression of inflammatory molecules, MIP-1α and ICAM-1 by LBE and RA indicates less activated hepatic stellate cells, following less α-SMA and COL1A1, the markers of liver fibrosis." (PMID 32331258, 2020). "Here, our study demonstrated that ANRIL was significantly decreased in activated HSC and liver fibrosis tissues, while Col1A1, α‐SMA and DNMT3A were significantly increased in activated HSC and liver fibrosis tissues." (PMID 31961061, 2020).
liver fibrosis (continued). "Regarding liver fibrosis, we confirmed that not only Tgf-β1 mRNA expression but also that of Col1a1, Timps, and Ctgf mRNA expressions were correlated with liver fibrosis in the Cx32ΔTg-MCDD model." (PMID 32833043, 2020). "Similar to the CCl4-induced fibrosis model, Med23 silencing also resulted in increasing mRNAs related to liver fibrosis, including Col1a1, Col3a1, Tgfβ1, Pdgfβ, Tgfβr1, Pdgfrβ, and Timp1." (PMID 31805036, 2019). "Galunisertib (LY2157299), an oral inhibitor of TGFβRI kinase, inhibited the phosphorylation of Smad2/3 in a liver fibrosis model, thereby suppressing the production and maturation of COL1A1." (PMID 31614978, 2019). "Fermented black radish was also shown to mitigate liver fibrosis through the inhibition of alpha‐smooth muscle actin, transforming growth factor beta‐1, and collagen type I alpha 1 chain." (PMID 31660146, 2019). "Next, we explored the correlation between serum circMTO1 and the markers of liver fibrosis such as Col1A1 and α‐SMA." (PMID 31148365, 2019). "Both curcumin prevention and treatment reduced molecular markers of hepatic fibrosis (Col1a1 mRNA) and inflammation (TNF‐α, SPP1 mRNA)." (PMID 30009570, 2018). "We observed by qPCR analysis an increased expression of αSma, a marker for stellate cell activation and Col1a1, a marker for liver fibrosis in Rbpj−/− mice." (PMID 30501048, 2018). "Since MT is an anti-liver fibrosis monomer, the matrinic acid compound library constructed in our lab was screened by the high-throughput screening model based on COL1A1 promotor taking epigallocatechin gallate (EGCG) as the positive control." (PMID 29976890, 2018). "A significant increase in gene expression for TGF-β, α-SMA, and Col1a1 was observed in mice affected by liver fibrosis and treated with control solution compared to healthy mice, whereas no significant variation was shown for GGT expression levels." (PMID 30647809, 2018). "In line with the hepatic fibrogenesis in HFrD-fed A/AHep mice, there was strongly increased expression of liver fibrosis marker genes (Col1A1, Col3A1, Timp1 and Pdgfr-β) in the livers of the HFrD-fed A/AHep mice." (PMID 28781602, 2017). "Knockdown of HRC reduced the expression of α-SMA, along with other genes relative to liver fibrosis, such as Col1A1, Col3A1 and CTGF." (PMID 27881436, 2017). "UCM was the default to inhibit the formation of COL1A1 toward the development of liver fibrosis (p > 0.05)." (PMID 28594374, 2017). "The expression levels of several hepatic fibrosis markers such as alpha smooth muscle actin (αSMA), collagen type 1 alpha 1 chain (Col1A1), fibronectin 1 (FN1), PCNA and tissue inhibitor of metalloprotease 1 (TIMP1) were tested by RT-qPCR." (PMID 29125588, 2017). "The mRNA markers for hepatic fibrosis (Col1a1 and Timp1 mRNA) showed a pattern similar to that of hepatic TG." (PMID 28159867, 2017). "Of particular note, BRD4 promotes the expression of Col1A1, which encodes Type I collagen, in response to exogenous TGF-β, thereby leading to both lung and liver fibrosis." (PMID 27990121, 2016). "Despite the increase in fibrosis in LysM-Wls mice, mRNA levels of the key interstitial collagens contributing to liver fibrosis, Col1a1, Col1a2 and Col3a1, were comparable between LysM-Wls and littermate controls." (PMID 26473015, 2015). "Reduced mRNA expression of Col1a1 in PdgfrαWT/nGFP mice after chronic CCl4 injection was accompanied by a reduction in liver fibrosis, as assessed by picrosirius red staining, a histochemical assay for tissue fibrosis." (PMID 24667490, 2014). "It has recently been shown that decreased miR-29 expression results in the excessive production of Col1A1 in cardiac fibrosis and liver fibrosis patients." (PMID 23236489, 2012).
liver fibrosis (continued). "Interestingly, the expression levels of CXCL13, TNFSF8, and TNFRSF8 correlated negatively with the expression of retinol binding protein 4 (RBP4), which is decreased in cirrhosis, and positively with the expression of COL1A1, which reflects liver fibrosis." (PMID 40014629, 2025). "Studies have shown that activation of ferroptosis in mouse HSCs using Erastin increased reactive oxygen species (ROS) and malondialdehyde (MDA) levels, decreased glutathione peroxidase 4 (GPX4), glutathione (GSH) and COL1A1 levels and alleviated liver fibrosis." (PMID 40278581, 2025). "Similarly, the levels of mRNA related to liver fibrosis (Col1A1, Acta2, Timp1, and Tgfb1) were significantly increased in the DM group, which were significantly reduced by the LFD treatment." (PMID 41374037, 2025). "Furthermore, the mRNA and protein levels of alpha-smooth muscle actin (α-SMA) and collagen type I alpha 1 (COL1A1) were determined to assess liver fibrosis." (PMID 41390431, 2025). "Since hedgehog signaling pathway activation increases COL1A1 mRNA expression in myofibroblasts and promotes myofibroblast accumulation and liver fibrosis, we examined whether a hedgehog pathway activator would induce fibrosis in microHOs." (PMID 39656528, 2024). "Importantly, PI3K-AKT and focal adhesion-related proteins, such as PDGFRβ, PIKR3R1, ITGB5, COL1A1, COL6A1, COL6A3, and LAMA5, are mainly associated with liver fibrosis." (PMID 38469403, 2024). "Moreover, LECT2 is also considered a pivotal gene in BA liver fibrosis to boost fibrosis by triggering fibrous genes such as α-smooth muscle actin and collagen type I alpha 1 Chain." (PMID 38881894, 2024). "It was reported that HF could significantly promote the expression of α-SMA, COL1A1, and the proliferation of LX-2 cells, indicating that the parasite components in HF participated in the development of liver fibrosis by activating HSCs." (PMID 38643149, 2024). "Additionally, a high-throughput drug screening model based on the COL1A1 promoter has been established to identify potential anti-hepatic fibrosis drugs." (PMID 39845977, 2024). "TGFβ1 and Col1a1 were analyzed as factors involved in liver fibrosis." (PMID 36835211, 2023). "The results of Masson staining showed the reduction of collagen deposition in Zbp1 siRNA-GeRP-treated injured livers, which was in accordance with the decreases of Acta2 (α-SMA, the marker of liver fibrosis), Col1a1 (Col I) and Col3a1 expressions in Zbp1 siRNA-GeRPs-injection groups." (PMID 36859525, 2023). "Similarly, indirect evidence for the regulation of Col1a1 by the YAP/TAZ proteins has been provided: transgenic mouse models of liver fibrosis overexpressing YAP proteins displayed an increase in collagen deposition and increased Ctgf mRNA levels." (PMID 37373151, 2023). "Our data demonstrate, that PDGFRβ-P2A-CreERT2 specifically and efficiently marks over 90% of retinoid positive HSCs in healthy and fibrotic liver in mice upon tamoxifen injection, and that those cells give rise to Col1a1-expressing myofibroblasts in different models of liver fibrosis." (PMID 37147343, 2023). "Therefore, our study investigated the role of COL6A1, COL6A2, COL6A3, and COL1A1 expressions on liver fibrosis in BA patients in Indonesia." (PMID 38041174, 2023). "A recent study demonstrated the involvement of COL1A1 in liver fibrosis through miRNA-29 signaling." (PMID 38041174, 2023). "Curcumin inhibited the expression of α-SMA and pro-COL1A1, and inhibited liver fibrosis." (PMID 37663261, 2023). "mRNA analysis showed increase in gene expression for markers of liver fibrosis (col1A1 and α-sma)." (PMID 37707950, 2023). "Decreased Col1a1 mRNA levels as a consequence of miRNA regulation has been suggested following Lin28B (a suppressor of miRNA synthesis) knock-out in a mouse model of alcohol-induced liver fibrosis." (PMID 37373151, 2023).